IL6 (interleukin 6)
Diseases named in the same sentence as IL6 in open-access papers (continued):
Sharing a sentence is not in itself a finding about the gene and the disease.
tumor (continued). "Additionally, vitamin D can downregulate the expression of genes that promote inflammation and tumor growth, including pro-inflammatory cytokines like interleukin-6 (IL-6) and tumor necrosis factor-alpha (TNF-alpha)." (PMID 38927564, 2024). "It was demonstrated that proinflammatory cytokines released by tumor tissue and related inflammatory cells, such as IL-4 and IL-6, could affect the synthesis of albumin in hepatocytes, thus decreasing albumin levels." (PMID 39440062, 2024). "In HCV infection, the TGF-β signaling pathway is altered, resulting in the progression of liver injury, the tumor suppressor activity of TGF-β changes to fibrogenic leading to the risk of HC, IL-1, IL-23, IL-6 and lymphotoxins were involved in the development and progression of inflammation in HC." (PMID 39608222, 2024). "Notably, cluster C6 displayed high expression of genes involved in interferon-γ/α response, IL-6/JAK/STAT pathway, angiogenesis and epithelial-mesenchymal transition (EMT), and all these are associated with tumor maintenance and metastasis." (PMID 38169544, 2024). "In vivo studies have hypothesized that that chronic stress affects tumor angiogenesis by the chronic release of proangiogenic factors (e.g., VEGF, IL-6, TGF-α and -β and TNF-α) and causes immune suppression, which can increase the risk of cancer development." (PMID 38275892, 2024). "Additionally, the SCFA butyrate has the capacity to mitigate the suppression of pro-inflammatory signals in macrophages, such as IL-6, consequently inhibiting tumor growth." (PMID 39044834, 2024). "They secrete anti-angiogenic or immunostimulatory cytokines and chemokines to stimulate inflammatory responses, including TNF-α, interleukin (IL)-1β, IL-2, IL-6, IL-12, and IL-23, and may also act as tumor-suppressors." (PMID 39169402, 2024). "IL-6 is a pleiotropic cytokine and can promote M2 polarisation of macrophages in sites of inflammation and tumour microenvironment and could have a role in the M2 skewed profile of macrophage infiltration in VS." (PMID 38480935, 2024). "For instance, although interleukin‐6 (IL‐6) is generally recognized for its tumor‐promoting effects, IL‐6 released from skeletal muscle during exercise enhances insulin sensitivity, stimulates the production of anti‐inflammatory cytokines, and reduces proliferation and DNA damage in cancer cells." (PMID 39492832, 2024). "Moreover, when synthesized by tumor cells, IL-6 acts in a paracrine way inducing fibroblast differentiation into CAFs." (PMID 39015505, 2024). "However, acute IL-6 activation can enhance the immune response by recruiting cytotoxic T-cells to target tumor cells, reflecting its complex role in cancer progression." (PMID 39766056, 2024). "Other than its known roles in promoting tumor progression, it has recently been discovered that IL6-dependent STAT3 signaling plays a central role in inflammation-mediated cancer, obesity or metabolic reprogramming, cancer stem cells, and pre-metastatic niche formation." (PMID 38320998, 2024). "Additionally, IL-6 released from ASCs promotes tumor progression by regulating gene expression involved in proliferation, such as a marker of proliferation Kiel 67 (MKI67) and proliferating cell nuclear antigen (PCNA)." (PMID 39123496, 2024). "Furthermore, a subset of studies has revealed that tumor-associated macrophages can wield influence over the EMT program in CRC through the secretion of SASP molecules, such as IL-6, thereby intensifying CRC metastasis." (PMID 38683136, 2024). "The CIDEA-mediated degradation of AMPK is essential for tumor-induced lipolysis; hence, IL-6-induced CIDEA expression may explain the excessive fat catabolism in cachexia." (PMID 38474057, 2024). "Notably, the migratory tumor subtype was closely linked to genomic alterations of EGFR, related to the tumor-promoting behavior of IL6-positive inflammatory tumor-associated fibroblast, and contributing to poor prognosis." (PMID 38892065, 2024).
tumor (continued). "Chronic exposure to pro-inflammatory cytokines, TNF-α, IL-6, and insulin-growth-factor-binding proteins (IGFBPs) has been reported to induce insulin resistance by directly impairing insulin signaling activation while simultaneously fueling tumor activation." (PMID 38791998, 2024). "Intense FcεRI staining was observed for both the IL-6 KO and WT tumor sections." (PMID 39195287, 2024). "Moreover, various studies demonstrated increased IL-6 levels in both tumor tissues and serum samples of human CRC patients compared to healthy controls." (PMID 39030280, 2024). "To determine the abundance of IL6 in HPV − and HPV + HNSCC, we established orthotopic tumors by intramucosal injection of HPV − mouse cancer MOC2 cells or HPV + mouse cancer TC-1 cells into C57BL/6 mice and then measured IL6 concentration in the peripheral serum extracted from these tumor models." (PMID 38468260, 2024). "In addition, IL-6 can aggravate tumor invasion through its role in the STAT3-Twist signaling pathway." (PMID 38728503, 2024). "In studies on tumors, resveratrol has been proven to downregulate the production of pro-inflammatory cytokines, such as TNF-α, IL-6, and IL-1β, and mitigating the inflammatory milieu within the tumor microenvironment hinders the development of angiogenesis, tissue invasion, and metastasis processes." (PMID 39458478, 2024). "The IL-6 cytokine family also exerts profound effects on immune cells, promoting the differentiation of T cells into Th17 cells, which secrete pro-inflammatory cytokines that further support tumor growth." (PMID 39421736, 2024). "The underlying reasons for this correlation could be multifaceted, involving complex interactions between the RDW and various inflammatory markers, cytokines like IL-6 and tumor necrosis factor-alpha, which are known to influence the behavior of tumor cells." (PMID 38791033, 2024). "In tumorigenesis, IL-6 promotes tumor growth and metastasis in various cancer types (42, –, 44)." (PMID 38564670, 2024). "IL-6 expression showed moderate correlation with tumour size." (PMID 38480935, 2024). "While certain cytokines, such as members of the IFN family, can directly induce apoptosis in tumor cells, some cytokines such as IL-6, TNFα, and TGFβ can enhance cell proliferation and resistance to induced cell death, ultimately fostering tumor growth and progression." (PMID 39204319, 2024). "This can be attributed to the low expression of CTLA-4 by IL-17-producing Tregs, which leads to Forkhead box O 3 (FoxO3) inactivation in DCs and the activation of the IL-6 production-STAT3 signaling pathway in tumor cells, ultimately promoting their proliferation." (PMID 38317142, 2024). "Continuous infusion of the anti-IL-6 antibody, or an isotype control antibody, was initiated at two different timepoints, with the first being at 10 or 12 days after tumor inoculation, a stage when the AP has increased IL-6 and AP neurons show elevated activity, but cachexia has not yet started." (PMID 38824130, 2024). "Similarly, replacement therapy with tumor suppressor miR-34a can downregulate IL6 expression and suppress the pro-inflammatory effects associated with IL6/STAT3 activation, thereby aiding tumor suppression and invasion control in OC." (PMID 39766086, 2024). "We noted that apatinib inhibited IL-6-mediated upregulation of PD-L1 in tumor cells." (PMID 38532022, 2024). "We observed a significant correlation between peak IL-6 levels and tumor burden." (PMID 39399502, 2024). "The treatment with Tarceva or NuF could inhibit tumor IL-6 protein expression, whereas the NuF treatment could inhibit the PTHrP expression at both the protein and gene levels." (PMID 39273055, 2024). "Furthermore, TAMs also secrete interleukin-6 (IL-6), which promotes angiogenesis, providing support for tumor growth and development." (PMID 39200233, 2024). "Likewise, therapeutic administration of neutralizing IL-6 antibodies to WT hosts with established KPT tumor allografts reduced their growth." (PMID 39128004, 2024).
tumor (continued). "Additionally, in peritoneal LAMs, the expression of CD206, CXCL9 and iNOS initially increases and subsequently decreases as the tumor progresses, whereas the expression of IL-1β and IL-6 first decreases and then increases." (PMID 38779660, 2024). "STAT3 can upregulate the expression of miRNAs by directly binding to their promoters, thereby forming a STAT3/miRNA/IL-6 loop or affecting the expression of downstream target genes, ultimately promoting tumor cell proliferation, invasion, and migration, and accelerating tumor growth." (PMID 38172648, 2024). "IL‐6 in the TME derives from tumor cells, myeloid cells, and fibroblasts." (PMID 37452653, 2024). "IL-6 and IL-6 receptor are secreted by peri-tumor endothelial cells and macrophages, respectively." (PMID 38943171, 2024). "The tumor cells of iCCA shared activated signaling pathways, such as IL-6/STAT3, Wnt, TGF, and TNF." (PMID 39410050, 2024). "Thus, loss of genes encoding NF1, TSC1, or TβRII resulted in tumor cell-autonomous inflammatory reprogramming through the activation of the JAK-STAT3/6 pathway and resulted in increased production of IL6 and IDO1." (PMID 38997291, 2024). "The downregulated IL-6 pathway may indicate an immunosuppressive microenvironment, leading to the immune escape of tumor cells." (PMID 38881895, 2024). "Tumor growth induces tissue inflammation, including IL‐6, which elevates CRP levels." (PMID 38923354, 2024). "Tumor-educated MSCs can further activate and release the chemoprotective and immunomodulatory factors including CXCL1, CXCL2, and IL-8, favoring tumor progression in which MSCs generated CXCL2, VEGF, TGF-β, and IL-6 can further raise tumor aggressive phenotype by boosting tumor angiogenesis." (PMID 38951845, 2024). "It has been suggested that modifications in the tumor microenvironment, such as increased levels of TNF-α, interferon-gamma, T cell infiltration, and reduced levels of interleukin-6 and interleukin-8, could be associated with irAEs and treatment outcomes." (PMID 39717410, 2024). "The hypoxia of tumor microenvironment suppresses metabolic activity and viability of DCs, or tumor cells reduce the immune activity of dendritic cells directly by secreting interleukin-6 (IL-6), interleukin-10 (IL-10), and transforming growth factor-β (TGF-β)." (PMID 38231384, 2024). "The IL-6 anti-inflammatory factor secreted by Th2 cells can produce a large amount of immunoglobulin by stimulating B cells, which have anti-infective, inhibit, and kill tumor cells." (PMID 38328420, 2024). "Finally, patients with tumor, or high IL-6 or high IL-10 expression and lower CD8+ or lower NK levels exhibited a significantly shorter survival time." (PMID 38173531, 2024). "Meanwhile, LPS induces the elevation of IL-6, which may influence the tumor inflammatory microenvironment through a similar mechanism." (PMID 39497925, 2024). "Thus, we surmised that IL-6 was produced directly from the tumor tissue and IL-6 expression was potentiated through the IL-6/STAT3 signaling pathway." (PMID 38389627, 2024). "Lowering E2F1 expression or blocking the deleterious E2F1-STAT3/IL-6 axis to modulate the tumor secretome could therefore improve antitumor responses and reduce adverse effects when interleukins and ICIs are used in combination." (PMID 39544930, 2024). "IL6 is a proinflammatory gene, but it also promotes tumor cell proliferation." (PMID 39329063, 2024). "For example, CAFs could secrete vascular endothelial growth factor (VEGF) to regulate the tumor vascular network, and interleukin 6 (IL-6) to foster the differentiation of myeloid-derived suppressor cells (MDSCs) and suppress cytotoxic T cells." (PMID 38728370, 2024). "Additionally, by promoting angiogenesis and helping the tumor avoid immune monitoring, IL-6 exerts an extrinsic effect on other cells inside the TME, resulting in a pro-tumor environment." (PMID 38803729, 2024). "For example, IL-6 can promote tumor cell proliferation, invasion, and anti-apoptosis." (PMID 39200381, 2024).
tumor (continued). "For instance, the IL-6, platelet-derived growth factor (PDGF), and matrix metalloproteinases (MT-MMPs) such as MMP-2, MMP-9, MMP-14 and alpha-1 type I collagen (encoded by COLA1) secreted by tumour cells are known to influence MSC activity." (PMID 39120301, 2024). "Our study provides strong evidence to support the hypothesis that the VPS35/YAP/IL-6 loop bridges the interaction between tumour cells during gastric malignant progression." (PMID 37950040, 2024). "Notably, iCAFs, particularly through IL-6 and IL-8 production, significantly influence the dialogue within the tumour ecosystem for various malignancies." (PMID 39676864, 2024). "Taken together, our results show that targeting VPS35- and IL-6/STAT3-mediated tumour interactions may be an attractive therapeutic strategy for GC." (PMID 37950040, 2024). "Phosphorylated STAT3 (pSTAT3) was upregulated in BMDMs treated with Se CM compared to CM from normal tumor cells (Ctrl), which could be rescued by IL-6-neutralized CM." (PMID 38323313, 2024). "Furthermore, ailanthone induced the expression of the inflammatory factors TNF-α, IL-1β, and IL-6 in tumour tissues." (PMID 39723259, 2024). "Indeed, once activated, PSCs secrete a large number of inflammatory signals that can promote angiogenesis, proliferation and migration of tumor cells, including IL-1, IL-6, IL-8, IL-10, VEGF, PDGF, FGF, type I collagen and CXCL12." (PMID 39020414, 2024). "The AP network – including the AP, NTS, PBN, PVN, BNST, and CeA, which are interconnected – show robust hyperactivity during cancer progression, starting from the pre-cachectic state when IL-6 starts to elevate in the AP till cachectic state in different tumor models." (PMID 38824130, 2024). "Thus, the inhibition of IL-6 can eliminate sensitive IL-6 clones of malignance cells creating free tumor environment niches, although favoring the proliferation of other malignant clone cells whose growth is triggered by other growth factors." (PMID 38731966, 2024). "Neither therapeutic IL-6 inhibition nor IL-6 cytokine deficiency in the host environment led to a significant increase in CD8 T cell tumor infiltration." (PMID 39128004, 2024). "Similarly, tumor expression levels of IL-6 and IL-6 receptor (IL-6R) were prognostic factors for over-all survival and metastasis-free survival in soft-tissue sarcoma patients." (PMID 39518029, 2024). "We found that concentrations of both IL-6 and TNFα were significantly high in the matched non-tumor and the matched tumor groups than healthy people (H) (P = 0.0289 and P < 0.001 for IL-6, and P = 0.001 and P < 0.001 for TNFα, respectively), whereas IL-1β was not (P = 0.7156 and P > 0.9999)." (PMID 38166062, 2024). "The production of IL-6 by PBMCs in autologous cultures depends on the tumor burden." (PMID 39518029, 2024). "Furthermore, the two scaffolds significantly upregulated the gene expression levels of NOTC-1, HIF-1α, and IL-6 that are involved in the signaling cascade between CSCs and the tumor stem niche, promoting resistance and metastasis." (PMID 38791452, 2024). "In addition, IL-6 positively correlates with tumor TNM stage and is associated with depth of tumor infiltration and lymph node metastasis in CRC." (PMID 39139454, 2024). "Soluble GP130 inhibited signaling from IL-6 and other tumor-promoting cytokines." (PMID 38900577, 2024). "However, future experiments will be required to verify that CSF3 and IL-6 are involved in tumor promotion in this model." (PMID 39338937, 2024). "They found increased IL-6, IL-1β, MDSCs, and tumor regrowth." (PMID 38543305, 2024). "IL-6 in the TME recruits MDSCs to participate in the drug resistance of tumor therapy and may be related to CD8+ Tex, but the clear mechanism needs further exploration." (PMID 39372416, 2024).
tumor (continued). "Moreover, the expression of various CAF-associated cytokines, including IL-1, IL-6, IL-8, CCL5 and CXCL12, in ADSCs was significantly elevated after coincubation with sEV derived from tumor cells and ascites, as detected by RT–qPCR." (PMID 38233863, 2024). "Functionally, M1 type macrophages activate the immune response mainly through the production of pro-inflammatory cytokines (e.g., tumour necrosis factor-α [TNFα], interleukin-1β [IL-1β], interleukin-6 [IL-6]) and inhibit tumour growth and spread by phagocytosis and killing of tumour cells." (PMID 39070147, 2024). "By creating an inflammatory microenvironment within the tumor, IL‐6 and IL‐1β may promote tumor‐cell proliferation by activation of transcription factors and angiogenesis by the induction of key factors such as vascular endothelial growth factor (VEGF)." (PMID 38217262, 2024). "The tumor microenvironment plays a crucial role in cancer development because it modifies the properties of cancer cells; this is integrated by immune and connective cells that secrete cytokines, such as IL-6." (PMID 39201674, 2024). "Thus, IL-6 represents a central hub in the close tumor-stroma dialogue necessary for tumor growth and progression." (PMID 39015505, 2024). "The dysregulation, indicated by an elevated IL-10/IL-6 ratio, may create a less conducive tumor microenvironment for PD-1 antibody therapy." (PMID 39227388, 2024). "IL-6 pathway is also reported as a key player in the mobilization of anti-tumor T cell responses." (PMID 38881895, 2024). "The importance of IL-6 as a biomarker in various cancers is increasingly recognized, highlighting its role in oncogenesis and tumor progression, with TAM-derived IL-6 pivotal in activating the STAT3 cascade, thereby upregulating EMT-TFs and propelling tumor progression." (PMID 39286635, 2024). "Furthermore, both treatments were effective in inhibiting tumor growth in EA and ES by modulating the levels of interleukin (IL)-6 and tumor necrosis factor (TNF)-α, decreasing mast cells numbers and inducing apoptosis." (PMID 39861087, 2024). "Indeed, the addition of the inactivating mouse-IL-6 antibody to CM-CAF D + Q alleviated the stimulatory effects on the migratory activity of tumor cells." (PMID 38612842, 2024). "Additionally, it significantly inhibits the expression of NF-κB signaling-dependent proinflammatory genes IL-6 and IL-1B through RAD51, thus blocking the STING-associated anti-tumor immunity in stromal tumor-infiltrating lymphocytes (sTIL)." (PMID 39638799, 2024). "The source of IL-6 within the CRC microenvironment may include tumor cells themselves, as well as TAMs and cancer-associated fibroblasts (CAFs)." (PMID 38689325, 2024). "Notably, high IL-6 levels correlated with adverse features such as poorly differentiated histology, higher tumor burden, and low albumin levels, indicating a stronger likelihood of poorer prognosis." (PMID 38672257, 2024). "Furthermore, increased levels of IL-6 suppressed radiation-induced cell death and blockade of IL-6 signaling by tocilizumab sensitized OSCC tumor cells to radiation." (PMID 38957610, 2024). "In the same experimental setting, we also measured the release of pro-tumor IL-8, IL-6, and TGF-β." (PMID 39125655, 2024). "The effects of neutrophils and IL-6 on tumor immune invasion had been demonstrated in recent years." (PMID 38430269, 2024). "The positive correlation found in tumor biopsies suggests that although several factors may be involved in CD155 regulation, the elevated level of IL-6 in the TME plays an important role in the induction of CD155 overexpression in tumor cells." (PMID 39596207, 2024). "The secretion of IL-6 by HCC tumor cells, macrophages, and DCs is observed." (PMID 38426090, 2024).